IGSF22 (immunoglobulin superfamily member 22)
Synonyms: FLJ37794; IGFN2
Tractability: No criterion of Open Targets' tractability assessment is met for any kind of drug.
Gene: Protein-coding gene on chromosome 11 (18,704,312 to 18,726,230, reverse strand). Ensembl gene ENSG00000179057.
Subcellular location (Human Protein Atlas): Mitochondria
Genetic constraint (gnomAD): Loss-of-function variants: 106 observed, 119.3 expected, observed/expected ratio (o/e) 0.89, 90% interval 0.76 to 1.04. The synonymous counts are far from expectation, so gnomAD's model fits this gene poorly and the ratio says little. Missense variants: 1,447 observed, 1,713.1 expected, observed/expected ratio (o/e) 0.84, 90% interval 0.81 to 0.88. Synonymous variants: 548 observed, 675.43 expected, observed/expected ratio (o/e) 0.81, 90% interval 0.76 to 0.87.
Homologues: Orthologues: chimpanzee IGSF22 (99% identical), macaque IGSF22 (97% identical), dog IGSF22 (92% identical), zebrafish igfn1.3 (36% identical), zebrafish igfn1.2 (34% identical), zebrafish igfn1.4 (30% identical), zebrafish igfn1.1 (13% identical). Paralogues in human: MYBPC2 (23% identical), MYBPC1 (22% identical), MYBPC3 (21% identical), MYOM1 (15% identical), MYOM2 (15% identical), OBSL1 (14% identical), MYOM3 (14% identical), FNDC3A (12% identical), FNDC3B (11% identical), MYBPH (10% identical), MYBPHL (7% identical).
Diseases named in the same sentence as IGSF22 in open-access papers:
IGSF22 is named in the same sentence as 1 disease in open-access papers, as found by Europe PMC text mining. Sharing a sentence is not in itself a finding about the gene and the disease. The quoted sentences say what the papers report.
renal carcinoma (1 paper, 2020). A carcinoma arising from the epithelium of the renal parenchyma or the renal pelvis. "IGSF22 is known to be similar to cytoskeletal proteins in its structure, with a one-nucleotide substitution in the IGSF22 gene associated with the development of renal carcinoma." (PMID 32046176, 2020).